CLDN1 (claudin 1)
Diseases named in the same sentence as CLDN1 in open-access papers (continued):
Sharing a sentence is not in itself a finding about the gene and the disease.
Stroke (22 papers, 2018 to 2025). Sudden impairment of blood flow to a part of the brain due to occlusion or rupture of an artery to the brain. "Previous study shows ischemic stroke causes reduction of occludin, claudin-1, and ZO-1 of the blood-brain barrier at 14 days post-stroke." (PMID 38107410, 2023). "A separate study showed that claudin-3 knockout mice did present with exacerbated ischemic lesion in a mouse model of stroke resulting in BBB breakdown associated with a decrease in claudin-1 expression and shorter TJ strands." (PMID 36320068, 2022). "The Veh-treated stroke mice exhibited loss of Claudin-1 protein expression in IL LVCP." (PMID 35413993, 2022). "We found that the structure of intestinal barrier integrity was badly damaged in aged-FTG mice on post-stroke day 3, with Claudin-1 and Occludin barely visible in immunofluorescence (IF) images." (PMID 39371609, 2024). "Targeting CLDN1 using either shRNA or pharmacological approach has been shown to improve BBB recovery after stroke." (PMID 37490345, 2023). "We further examined changes of claudin-1 protein in LVCPs in sham or stroke mice at 1, 5, and 7 days post-tMCAO by Western Blotting." (PMID 38107410, 2023). "The analysis of post-stroke human and mouse blood microvessels indicated that Claudin-1 was highly expressed in leaky brain microvessels and there was a corresponding decrease in Claudin-5 expression." (PMID 35887162, 2022). "Using a specific peptide that targets claudin-1 reduced BBB permeability after stroke and consequently improved neurological recovery." (PMID 36320068, 2022). "A recent study showed that claudin-1 replaced claudin-5 at the TJs of brain capillary endothelial cells during the regeneration phase after stroke." (PMID 34795584, 2021). "Claudin-1 upregulation has been found in conditions such as stroke, where it appears to impair interactions with other tight junction components due to its incorporation." (PMID 34867185, 2021). "In this regard, a recent study showed that claudin-1 replaces claudin-5 at the TJ of brain capillary endothelial cells during the regeneration phase after stroke." (PMID 32138745, 2020). "Claudin-1 is rarely expressed in the normal BBB but is strongly expressed in leaky brain microvessels after stroke." (PMID 32917229, 2020). "Claudin-1 protein expression was then returned to the control level by 7 days post-stroke." (PMID 38107410, 2023). "Besides, the other study reported that high expression of CLDN-1 resulted in blood–brain-barrier (BBB) leakiness during post-stroke recovery and targeting of CLDN-1 by a CLDN-1 peptide improved the permeability of brain endothelial barrier." (PMID 31952355, 2020). "The present study demonstrates that TZP mitigates stroke-induced BBB disruption in MCAO mice, potentially through modulation of Claudin-1 and C/EBP-α pathways." (PMID 40702450, 2025). "Its ability to restore Claudin-1-mediated TJ and BBB function through the activation of C/EBP-α signaling offers a potential approach to protect against stroke-induced neuronal damage." (PMID 40702450, 2025). "The expression of tight junction (TJ) proteins (zonula occludens-1 (ZO-1), occludin, and claudin-1) was downregulated, and transmission electron microscopy (TEM) showed broken TJ of the intestinal mucosa after stroke." (PMID 33642941, 2021). "In the acute phase after stroke, CRTC1 KO mice exhibited a statistically significant increase in TJAP-1 expression and Claudin-1 expression in comparison with WT mice." (PMID 34880207, 2021). "HDLs from stroke patients, independently of their outcome, significantly limited TNFα-induced expression of VCAM1 (increase) and CLDN1 (decrease) gene expression." (PMID 32708891, 2020). "For example, CLDN1 is not observed in a normal/healthy blood–brain barrier (BBB), but is highly expressed after stroke onset, causing leakage of the BBB." (PMID 35892692, 2022).
Stroke (continued). "In this study, TJAP-1 and Claudin-1 exhibited a significant increase in CRTC1 KO mice compared with WT mice, leading to BBB damage by Claudin-5/Claudin-1 dysregulation in the CRTC1 KO brain after stroke." (PMID 34880207, 2021). "The mRNA expressions of TJ proteins (ZO-1, occludin, and claudin-1) in mice decreased significantly in the stroke 1-day group (n = 5, p < 0.001), but the difference had not reached significance after 7 days of stroke (n = 5, p > 0.05)." (PMID 33642941, 2021). "Interestingly, HDLs from stroke patients were less prone to induce claudin-1 expression, regardless of the outcome." (PMID 32708891, 2020). "Therefore, our data indicate that the expression of claudin-1 and claudin-2 may be a result from TRPM4 suppression after stroke." (PMID 29569041, 2019). "Under the chronic status of stroke, upregulated CLDN-1 interferes with CLDN-5 incorporation into the TJ complex; CLDN-1 is not specific to the BBB, whose presence is concurrent with the endothelial proinflammatory phenotype and postpones the recovery of BBB integrity." (PMID 35464431, 2022).
inflammatory bowel disease (20 papers, 2009 to 2026). A spectrum of small and large bowel inflammatory diseases of unknown etiology. "Also, claudin-1 overexpression has been shown to mediate the pathogenesis of inflammatory bowel disease (IBD) and colitis-associated CRC." (PMID 38337789, 2024). "In overexpression mouse models, claudin-1 deregulation promoted inflammatory bowel disease (IBD) and colitis-associated cancer (CAC) susceptibility and severity but did not destabilize TJ integrity and permeability, suggesting that protumor functions of claudins are dependent on non-TJ functions." (PMID 34354941, 2021). "Claudin-1, ZO-1 and Occludin are typical structural proteins of epithelial tight junction, the higher expression of these proteins indicates there was decreasing risk of inflammatory bowel diseases." (PMID 27304828, 2016). "In intestinal epithelial cells, AHR activation improves intestinal barrier function by maintaining tight junction proteins (ZO-1, Occludin, and Claudin-1) and alleviates inflammation by inhibiting NF-κB, thereby improving inflammatory bowel disease." (PMID 41513604, 2026). "In general, dysregulation of Claudin 1 expression contributes to numerous autoimmune diseases including rheumatoid arthritis, type 1 diabetes, multiple sclerosis, or inflammatory bowel disease." (PMID 41481333, 2026). "In inflammatory bowel disease-associated CRC, elevated levels of Claudin-1 (CLDN1) activate Notch signaling, which subsequently triggers the PI3K/Akt pathway." (PMID 41294868, 2025). "Even though these claudins are considered to be barrier-sealing, in human biopsies their expression is elevated in active inflammatory bowel disease, and claudin-1 levels correlate with inflammatory activity." (PMID 38201850, 2023). "This is in keeping with our results that are the first to show AP-induced disruption of the claudin-1 distribution together with up-regulation of claudin-2, which is also the case in inflammatory bowel disease and destabilizes TJs." (PMID 19223985, 2009). "However, the expression of Claudin-1, which is related to inflammatory bowel diseases, was reduced in the P8 + Akk group." (PMID 40877018, 2025). "Similarly, Ahmed and Sheir concluded that the elevation of Claudin-1 in the duodenum and colon tissue sections confirmed the ameliorative regulation of Hibiscus in an inflammatory bowel diseases (IBD) model." (PMID 40788963, 2025). "It is speculated that the increased claudin-1 is related to inflammatory bowel disease." (PMID 34573663, 2021). "The intestinal proinflammatory immune factor and NF-κB could induce the decrease in claudin-1 expression inflammatory bowel disease, and BBR might regulate claudin-4 and claudin-2 expressions other than claudin-1 in claudin family." (PMID 28217099, 2017). "In particular, TNF-α plays a critical role in inflammatory bowel disease, where it can synergize with IFN-γ to regulate multiple tight-junction (TJ) proteins, including myosin light chain kinase, occludin, and ZO-1, as well as claudin-1 and claudin-2 (106, –, 109), which are also regulated by IL-17." (PMID 32958528, 2020).
endotoxemia (15 papers, 2015 to 2025). "LPS in the blood can cause endotoxemia, and the tight junction composed of transmembrane proteins, such as Occludin and Claudin-1, is disrupted, resulting in increased intestinal permeability and subsequent liver inflammation." (PMID 38892467, 2024). "The significant inverted correlation of occludin and claudin-1 expression with serum endotoxin concentration points towards a causal relationship between the disruption of enterocyte TJs and systemic endotoxemia in CKD." (PMID 38397970, 2024). "In the present study, the decreased occludin and claudin-1 expression in the intestinal mucosa was associated with systemic endotoxemia." (PMID 38255265, 2024). "Previously, it was reported that T2DM and dysbiosis of gut microbiota led to impaired intestinal permeability, increased LPS levels and caused endotoxemia and metabolic disorders, which eventually affected the expression of colon tight junction proteins (ZO-1, occludin, and claudin-1)." (PMID 36276816, 2022). "Heart failure, regardless of the type of ejection fraction, results in a significant decrease in enterocytic occludin and claudin-1 expression, which may represent an important cellular mechanism for the intestinal barrier dysfunction causing systemic endotoxemia and inflammatory response." (PMID 38255265, 2024). "It resulted in the reduction of endotoxemia (through LPSs) and pro-inflammatory cytokine (TNF-α, IL-6, and IL-1β) levels, with the increased expression of tight-junction associated proteins (claudin-1, occludin, and zonula occludens-1)." (PMID 41334341, 2025). "Our study showed an inverse correlation between intestinal occludin and claudin-1 expression and the extent of systemic endotoxemia." (PMID 38255265, 2024). "Occludin and claudin-1 expression inversely correlated with systemic endotoxemia (p < 0.05 and p < 0.01, respectively)." (PMID 38255265, 2024). "Intestinal occludin and claudin-1 were significantly decreased, and their expression was inversely correlated with systemic endotoxemia." (PMID 38397970, 2024). "A tight junction protein, Claudin-1, was down-regulated both in endotoxemia and by experimental MIR155 overexpression." (PMID 33618730, 2021). "Our animal experiment showed that external administration of IGF-1 reduced endotoxemia in liver cirrhotic rats via up-regulating occludin and claudin-1 expression in intestines." (PMID 26152281, 2015). "Although BFT has neither been shown to alter the fecal mucin level nor to alter the amount of bacterial metabolites, such as short-chain fatty acids, it increased tight-junction-related protein claudin 1 level in the colon, leading to improved gut permeability and attenuated endotoxemia." (PMID 32218475, 2020). "The aim of this study was to investigate whether the expression of the key TJ proteins occludin and claudin-1 is altered in the intestinal mucosa of patients with stage I–IV CKD or ESKD, contributing to systemic endotoxemia and inflammatory responses." (PMID 38397970, 2024).
prostate carcinoma (15 papers, 2010 to 2025). A carcinoma that arises from epithelial cells of the prostate gland. "It is suggested that the loss of tight junction protein, CLDN-1, is associated with cancer invasion, progression and the transformation into metastatic phenotype in prostate cancers." (PMID 31952355, 2020). "Reduced claudin 1 expression has been associated with loss of differentiation in prostatic carcinoma and has been suggested to be involved in the transformation of biological behaviours in gastric carcinoma." (PMID 23675182, 2010). "It is hypothesized that the loss of claudin-1 expression in prostate cancer could potentially indicate epithelial-mesenchymal transition." (PMID 38188015, 2023). "Particularly, this was most relevant in ERG-positive prostate cancer where increased claudin-1 expression predicts a favorable prognosis." (PMID 38188015, 2023). "Related studies have shown that ATP stimulation of P2Y2 receptors increases the expression of IL-8 and Snail, down-regulates the expression of E-cadherin and Claudin-1, and promotes the migration and metastasis of prostate cancer." (PMID 33330466, 2020). "A study reported that the lower expression of CLDN-1 correlated with higher prostate-specific antigen in prostate cancer." (PMID 31952355, 2020). "In the presence of ATP, expressions of Snail, IL-8 and MMP-3 were significantly increased in prostate cancer cells 1E8 and 2B4, while expressions of E-cadherin and Claudin-1 were prominently reduced." (PMID 25486274, 2014). "The 7 AJ and TJ proteins chosen were E-cadherin, α- and β- catenin, ZO-1, occludin, claudin 1 and claudin 7 and their expression was investigated using an in vitro model of prostate cancer progression." (PMID 24358122, 2013). "In CAHPV-10 and LNCaP prostate cancer cells, Claudin 1 was down regulated −10 fold (p = <0.001) and −100-fold (p = <0.001) respectively." (PMID 24358122, 2013). "Alterations in key AJ and TJ components such as α-catenin, E-cadherin, β-catenin and Claudin 1 have been hailed as potential biomarkers for prostate cancer progression but the majority of research has been carried out on individual molecules." (PMID 24358122, 2013). "Compared to PNT2, Claudin 1 levels were reduced in all prostate cancer cells." (PMID 24358122, 2013). "CLDN1 and CLDN5 are down-regulated in many cancers and also in mesotheliomas and low expression of these claudins are associated with more aggressive prostate cancer." (PMID 22905093, 2012). "On the contrary, PTGS2, CLDN1, and RPPH1 are negatively correlated with the prognosis of prostate cancer." (PMID 35813821, 2022). "The CLDN-1 and CLDN-7 members of the claudin family are primarily found to be downregulated in several invasive cancers including breast, esophageal, and prostate cancers." (PMID 31952355, 2020). "Studies have shown that knocking down the expression of P2X7R can significantly inhibit the expression of EMT/invasion-related genes Snail, Claudin-1, IL-8 and MMP-3 induced by ATP or BzATP, and inhibit the invasion, metastasis and EMT of prostate cancer cells." (PMID 40265472, 2025). "In prostate cancer cells, P2X7R was shown to promote invasiveness and metastatic properties and silencing its expression attenuated ATP- or BzATP-induced changes in the expression of EMT-related genes, Snail, E-cadherin and Claudin-1." (PMID 32825056, 2020).
lymph node metastasis (14 papers, 2014 to 2026). "In NPC, elevated levels of claudin-1 have been linked to lymph node metastasis and clinical staging." (PMID 37375849, 2023). "Loss of the tight-junction protein claudin-1 is associated with aggressive cancer behavior, deeper tumor invasion, advanced tumor grade, lymph node metastasis, PNI, LVI and recurrence." (PMID 30148861, 2018). "The association between GFRA3, IL-8 and CLDN1 and the clinical features such as post-operative survival, lymph node metastasis, gastric metaplasia and patient age may describe a more complex relationship which we have not further evaluated in this study." (PMID 26984265, 2016). "In particular, the intracellular expression of claudin 1 correlates significantly with a greater frequency of lymph node metastasis through the promotion of cell mobility." (PMID 36714681, 2023). "Claudin 1 (CLDN1) is associated with CRC tumor invasion, lymph node metastasis and tumor grade and stage." (PMID 35114976, 2022). "Claudin 1 expression correlates with better prognosis and lower rates of recurrence and lymph node metastasis." (PMID 31044387, 2020). "Claudin-4 high/claudin-1 low, claudin-4 high/claudin-7 low, and claudin-4 high/claudin-1 low/claudin-7 low types were also significantly correlated with lymph node metastasis, and showed worse survival." (PMID 31861759, 2019). "In ESCC tumors with lymph-node metastasis, the expression of Nm23H1 and CLDN1 significantly correlated to each other, whereas in ESCC tumors without lymph-node metastasis, such correlation did not exist." (PMID 27376780, 2016). "The results showed a significantly positive correlation between the expression of Nm23H1 and CLDN1 (γ=0.296, P=0.011) in surgical specimens, especially for the 34 tumors with lymph-node metastasis (γ=0.455, P=0.007)." (PMID 27376780, 2016). "According to our data, the expression of CLDN1 increased with the progression of cervical neoplasia and was correlated to lymph node metastasis." (PMID 27974683, 2016). "CLDN1 expression correlates positively with lymph node metastasis." (PMID 40687428, 2025). "Additionally, claudin-1 overexpression is significantly correlated with poor differentiation, lymph node metastasis, and survival rates among HSCC patients." (PMID 37686483, 2023). "It has been documented in a study of 83 TSCC specimens that high cytoplasmic expression of claudin-1 is linked to cervical lymph node metastasis, but not with disease progression." (PMID 37686483, 2023). "The strong positive staining of CLDN1 in the cervical lymph node metastasis group received a significantly higher score than the staining in the group with no lymph node metastasis of cervical cancer tissues." (PMID 27974683, 2016). "A lack of CLDN1 expression was related to only lymph node metastasis (P = 0.014)." (PMID 25393310, 2014). "CLDN1 expression was significantly higher in the LN− group, 55.3% (42/76) compared to 36.1% (35/97) in the LN+ group, suggesting that the absence of CLDN1 expression is related to lymph node metastasis (P = 0.014)." (PMID 25393310, 2014).